SAP30 (Sin3A associated protein 30)
Diseases named in the same sentence as SAP30 in open-access papers (continued):
Sharing a sentence is not in itself a finding about the gene and the disease.
tumour (5 papers, 2006 to 2025). "SCENIC predicted the top 4 transcription factors that differed expressed most between the two subgroups of tumour cells: SAP30, UQCRB, ZBTB33 and ZNF165." (PMID 40830065, 2025). "As expected, SAP30 KO blocked MDA-MB-231 tumor growth and distant metastasis to the lungs and liver, which was fully rescued by re-expression of WT SAP30." (PMID 37655663, 2023). "MLL1 KO1 also abolished SAP30-induced lung metastasis, tumor angiogenesis and lymphangiogenesis, and in vitro cell migration and invasion." (PMID 37655663, 2023). "Immunohistochemical staining with anti-endomucin and anti-podoplanin antibodies showed reduced tumor angiogenesis and lymphangiogenesis, respectively, in SAP30-KO mice." (PMID 37655663, 2023). "To confirm our findings from CRISPR KO studies, we used a short hairpin RNA (shRNA) targeting SAP30 and found that knockdown (Kæ D) of SAP30 similarly attenuated MDA-MB-231 tumor growth in NOD/SCID mice." (PMID 37655663, 2023). "Next, we studied the effect of SAP30 on circulating tumor cells (CTCs) in the orthotopic xenograft mouse model and found that CTCs were markedly eliminated in blood from mice bearing SAP30-KO1 or -KO2 tumors." (PMID 37655663, 2023). "Despite its effectiveness in tumor inhibition, loss of SAP30, SIN3, or MLL1 fails to eliminate primary tumors and distant metastasis in the mouse models." (PMID 37655663, 2023). "Expression of F186E/F200E mutant prevented the rescued effect of SAP30 on tumor growth and metastasis to the lungs and liver, although it slightly increased SAP30-KO tumor growth, maybe owing to its very high protein levels." (PMID 37655663, 2023). "To determine whether tumor angiogenesis is directly regulated by tumor cell–derived SAP30, we performed in vitro angiogenesis assay." (PMID 37655663, 2023). "SAP30 overexpression significantly increased growth of parental MDA-MB-231 tumors but not MLL1 KO1 tumors in mice, even after an extended breeding of MLL1-KO1 tumor–bearing mice for an additional 2 weeks." (PMID 37655663, 2023). "Surprisingly, the canonical gene silencing role was not essential for SAP30’s tumor-promoting actions." (PMID 37655663, 2023). "SAP30 is a core subunit of the SIN3 protein complex, an evolutionarily conserved multisubunit complex involved in development, stem cell pluripotency and self-renewal, cell cycle, senescence, intellectual disability, and tumor progression." (PMID 37655663, 2023). "Finally, we studied whether SAP30 controls TNBC cell colonization at distant organs, a critical step for metastatic tumor outgrowth." (PMID 37655663, 2023).
SAP30 also shares sentences with these, for which no sentence is quoted: acute myeloid leukemia (1 paper); colorectal carcinoma (1); encephalitis (1); hemorrhagic fever (1); Hepatitis (1); neurological diseases (1); prostate carcinoma (1); triple-negative breast carcinoma (1).